CD8A (CD8 subunit alpha)
Diseases named in the same sentence as CD8A in open-access papers (continued):
Sharing a sentence is not in itself a finding about the gene and the disease.
influenza (1,156 papers, 2003 to 2026). An acute viral infection of the respiratory tract, occurring in isolated cases, in epidemics, or in pandemics; it is caused by serologically different strains of viruses (influenzaviruses) designated A, B, and C, has a 3-day incubation period, and usually lasts for 3 to 10 days. "Indeed, LN-resident CD8α+ DCs as well as CD11b+ lung tissue DCs have also been implicated in influenza antigen transport, presentation and CD8+ T cell priming." (PMID 24699679, 2014). "Recently, it was demonstrated that CD8 T cell survival during influenza infection is promoted in the lung by trans-presentation of IL-15 by pulmonary CD8α+DCs." (PMID 23233854, 2012). "During influenza infection in vivo, however, two subsets of DC predominantly present viral antigens raising the possibility that non-CD8α DC, such as the migratory ones, are more easily accessed by infecting virus." (PMID 18301768, 2008). "In earlier studies, we used the three-way pDC sort to identify the CD8α DC as the primary subset involved in amplifying CD8+ T cell responses to influenza WSN-gB after i.v. infection." (PMID 18301768, 2008). "In addition, the virosome influenza vaccine induced significant proliferation of CD3e+CD8α+IFNγ+ T cells in swine, similar to previous studies in vaccinated mice, and pigs inoculated with a nanoparticle-adjuvanted influenza vaccine." (PMID 37587490, 2023). "Inclusion of CD8α ALN-1 in a prophylactic H3N2-based influenza vaccine fully protects mice against challenge infection with a high dose of a heterosubtypic pH1N1 influenza A virus, which correlated with the induction of strong, functional and long-lasting antiviral T cell responses." (PMID 32714571, 2020). "In earlier studies which suggested that CD8α DC were the sole DC subset responsible for presentation of influenza antigen, analysis of antigen presentation was restricted to segregation of DC populations into CD8α DC, CD8α− DC (termed double-negative (DN) DC) and plasmacytoid DC (pDC)." (PMID 18301768, 2008). "Alternatively, I-IFN signaling might be responsible for lymph-node CD8α+ DC crosspresentation in influenza-infected wild-type mice ensuring optimal DC maturation and increased processing of viral antigen from migratory DCs; despite tight control of virus replication by I-IFN." (PMID 22072965, 2011). "Furthermore, this GO analysis indicated that genes associated with the antiviral response to influenza (e.g., Ifi27l2a, Isg20, Oas1a, Isg15, Ifit1, Oasl1, and Ifit3) were strongly enriched in mice vaccinated with WIV alone as compared with mice vaccinated with WT IL-1β or CD8α ALN-1." (PMID 32714571, 2020). "One day prior to viral challenge, we found that CD8α ALN-1 promoted both CD8+ and CD4+ T cell responses against epitopes of influenza’s NP." (PMID 32714571, 2020). "Compared with those who did not receive the influenza vaccine, women who received the influenza vaccine had greater numbers of genes encoding T-cell surface markers (CD44, CD8A, CD62L and CD25) in breast milk." (PMID 39294774, 2024). "As CD8α ALN-1 was found to induce effective T cell responses to antigen with a vastly improved safety profile, we decided to evaluate its protective potential as an adjuvant in a model for prophylactic influenza vaccination." (PMID 32714571, 2020). "Furthermore, BATF3-/- mice that do not develop resident CD11b-CD8α+ DCs or migratory CD11b-CD103+ DCs have defective virus-specific T cell responses after WNV infection or influenza infections." (PMID 29408905, 2018).
colorectal cancer (978 papers, 2003 to 2026). A primary or metastatic malignant neoplasm that affects the colon or rectum. "Recently, it was shown that GBP1 and GBP4 are IFNG-dependent and were directly co-expressed with CD8A in colorectal cancer." (PMID 34487971, 2021). "Therefore, we sought to investigate the utility of Cu-64 labeled F(ab)′2 fragments for in vivo detection of CD8a+ T cells as a prognostic imaging biomarker of response to immunotherapy in an immunocompetent mouse model of colorectal cancer." (PMID 32086762, 2020). "In the human colorectal cancer (CRC) cohort, SIN3B expression levels were significantly negatively correlated with CXCL9/10/11 as well as CD8A, GzmA, and GzmB." (PMID 39316363, 2024). "It has been demonstrated that the increased expression of genes specific for cytotoxic T lymphocytes, as CD8α, granzyme B, or perforin was related to the absence of early metastatic invasion of colorectal cancer, and it could also improve patient survival." (PMID 23349906, 2013).
lung cancer (976 papers, 2007 to 2026). A malignant neoplasm involving the lung. "Meanwhile, CD8A was conformed as a biomarker to predict the clinical effects of nivolumab in lung cancer." (PMID 32316408, 2020). "In many respects, the high B cell/DC1 infiltration shaped an inflamed and immune-activated TME of lung cancer tissues, including adaptive immune resistance markers, CD8A, CD8B, immunomodulators (immunostimulants, MHC, receptors, and chemokines), and immune-related pathways." (PMID 34422829, 2021). "Immune C2, C3, and C6 had higher abundance of B cell and DC1, CD8A, CD8B, and hub genes, which indicated that immune C2, C3, and C6 lung cancer patients were suitable for immunotherapy and would benefit more from ICB therapy." (PMID 34422829, 2021). "In this study, 6 hub genes,NKX2-1,CD8A,SFTA3,IL2RB,IDO1, andCXCL9, which are all M1 macrophage coexpressed genes, were utilized to build the immunotherapy response model.NKX2-1 can regulate lung cancer growth by targeting the MAPK pathway." (PMID 38379417, 2024).
lymphopenia (757 papers, 2005 to 2026). Reduction in the number of lymphocytes. "Despite a large reduction in systemic toxicity, CD8α ALN-1 triggered lymphopenia in peripheral blood, comparable to WT IL-1β delivery." (PMID 32714571, 2020). "Consistent with findings from virulent Armenia2008 and CADC_HN09 infection of outbred pigs, we observed lymphopenia, which could be attributed to the loss of CD3+CD4+CD8α− and CD3+CD4+CD8α− T-and CD21+ B cells." (PMID 41510007, 2025). "The percentage of CD8α+ γδTCR+ cells increased as a proportion of the total number of γδT-cells in some animals after challenge, but this was not significant and is likely linked to the overall lymphopenia." (PMID 35891467, 2022). "By PV10d, NTV mice exhibited significant splenic lymphopenia: CD4+ and CD8a+ T cell frequencies decreased 48% and 37% versus CON (P < 0.01), respectively, with concomitant reduction in CD4+/CD8a+ ratios." (PMID 40709179, 2025).
glioma (695 papers, 2003 to 2026). A benign or malignant brain and spinal cord tumor that arises from glial cells (astrocytes, oligodendrocytes, ependymal cells). "They found that the nanodiscs platform in combination with a checkpoint blocker has the potential to induce neoantigen-specific CD8α+T cells infiltration into the glioma microenvironment." (PMID 37483515, 2023). "Induction of potent cytotoxic CD8α+T cells lymphocytes (CTL) responses responsible for development of robust anti-tumor immunological memory against glioma recurrence." (PMID 37483515, 2023). "Survival analysis revealed that low methylation levels of CD8A were related to worse prognosis in glioma, gastric cancer, and uveal melanoma cohorts but were associated with longer survival outcomes in ovarian cancer and KIRP cohorts." (PMID 36035168, 2022). "TIME cluster A exhibited the high expression profiles of ZEB1, TNF, and LAG3; while GZMA, CXCL9, CXCL10, and CD8A were relatively overexpressed in TIME cluster C. EMT is a common process of paramount importance in glioma occurrence and invasion." (PMID 34650972, 2021). "This was also observed in the human glioma survival analysis as high CD8a levels did not result in improved survival outcomes compared with low CD8A levels." (PMID 40842154, 2025). "Hence, we also investigated the relationship between CD8+ T cell marker CD8A and immune checkpoints in glioma." (PMID 37850692, 2024). "CLIC4 expression levels were positively correlated with specific markers of macrophages (CD80, CD86, MRC1), neutrophils (FCGR3A, FCGR3B), eosinophils (SIGLEC8, IL3RA), T cells (CD3D, CD4), CD8+ T cells (CD8A, CD8D), NK cells (NCAM1), and B cells (CD19) in glioma." (PMID 39595145, 2024). "Further verification suggested that gut microbiota deletion by antibiotics treatment could accelerate glioma development, attenuate TMZ efficacy and inhibit immune cells (macrophage and CD8α+ T cell) recruitment." (PMID 36927689, 2023). "IL13Ra2-CAR.CD28.ζ T cell proliferation resulted in the production of IFN-γ and TNF-α as well as facilitated phenotypically proinflammatory glioma microenvironment by triggering elevated levels CD4+ and CD8+ T cells and CD8α+ DCs as well as a reduction in Ly6G+ MDSC levels." (PMID 33204365, 2020). "Further investigation into SOCS1’s expression in gliomas, using single-cell sequencing data from the CGGA and GEO databases, indicated that SOCS1 predominantly accumulates in tumor cells and T cells, exhibiting a similar expression pattern to immune markers such as CD8A and IL7R." (PMID 39654174, 2024). "Notably, the methylation levels of CD8A manifested a significant negative correlation with level of CTLs in patients with glioma and uveal melanoma and a significant positive correlation with ovarian cancer cohort." (PMID 36035168, 2022). "We found a higher infiltration of antitumor immune cells (CD8+ T cells, TAMs, and NK cells) in gliomas with high PTPN2 expression, which is not in agreement with a previous study that reports a significant increase in the number of CD8α+ cells in PTPN2-deficient tumors." (PMID 29764444, 2018).
hepatocellular carcinoma (675 papers, 2007 to 2026). A malignant tumor that arises from hepatocytes. "Previous study also revealed the protective role of CD8A in the prognoses of hepatocellular carcinoma, metastatic melanoma and head and neck squamous cell carcinoma." (PMID 36230788, 2022). "The CD8A gene is a good prognostic predictor in nivolumab-treated patients with advanced hepatocellular carcinoma." (PMID 36505419, 2022). "For example, the exosomes derived from rat AD-MSCs were observed to accelerate intratumoral CD8α+ type I NK-T cell migration and increase circulating NK-T cells to exert antitumor immunity in rats with hepatocellular carcinoma (HCC)." (PMID 32117221, 2020).
ovarian carcinoma (672 papers, 2000 to 2026). A malignant neoplasm originating from the surface ovarian epithelium. "Using a syngeneic and orthotopic mouse ovarian cancer model, we performed the most reasonable evaluation of mouse CD8α+ DCs, which correspond to human CD141+ DCs." (PMID 36596856, 2023). "Our qRT-PCR analysis revealed a negative correlation between SNRPE expression and the expression of CD274 and CD8A in ovarian cancer tissues." (PMID 37090728, 2023). "In conclusion, mouse CD8α+ DCs derived from BM-HSCs decrease tumor progression and enhance antitumor immunogenicity against murine syngeneic ovarian cancer." (PMID 36596856, 2023). "The immune response and tumor response after stem-DC treatments demonstrated the effect of murine CD8α+ DCs against ovarian cancer." (PMID 36596856, 2023). "Most importantly, although our data indicate that CD8α+ DCs induce immune responses against ovarian cancer in the mouse model, the extrapolation to the human setting seems too far stretched." (PMID 36596856, 2023). "By integrating the expression levels of ICOS, TIGIT, TNFRSF8, and CD8A, ovarian cancer patients can be divided into 4 subgroups, which have different prognosis." (PMID 36157232, 2022). "To further confirm using independent datasets, we collected to our knowledge all the published ovarian cancer datasets (n>=40) that have detected the expression of PD-L1 and CD8A." (PMID 31523194, 2019). "For example, in ovarian cancer, the HR of PD-L1 is 0.84 [95%CI: 0.74-0.96], whereas the HR of CD8A is 0.92 [95%CI: 0.81-1.04]." (PMID 31523194, 2019). "It is well established that the expression of CD8A at the transcriptional level is a reliable indicator of CD8+ T-cell infiltration in ovarian cancer." (PMID 26448945, 2015). "Together, these results indicate that mouse CD8α+ DCs derived from BM-HSCs decrease tumor progression and enhance antitumor immune responses against murine ovarian cancer, suggesting that better DC vaccines can be used as an effective immunotherapy in EOC treatment." (PMID 36596856, 2023). "Moreover, the researchers verified their results that indicated that higher CD8A expression in the high expression of ICOS was related to an improved survival rate among ovarian cancer patients." (PMID 36157232, 2022). "Finally, the expression levels of ICOS, TIGIT, TNFRSF8, and CD8A were integrated for the purpose of grouping ovarian cancer samples by prognosis." (PMID 36157232, 2022). "To investigate whether GPC6 and TMEM132D expression correlates with CD8+ T-lymphocyte infiltration in early stage ovarian cancer, we used qPCR to quantify the mRNA levels of the CD8A marker in the same cohort of patients." (PMID 26448945, 2015). "Although CD8A is a classic established marker of T-cell infiltration in ovarian cancer, in our cohort of patients, the prognostic value of CD8A mRNA levels was statistically weak (p = 0.805) possibly due to the small size of the sample and the low number of deaths." (PMID 26448945, 2015). "Nevertheless, to the best of our knowledge, this is the first study to demonstrate the effectiveness of murine CD8α+ DCs in an ovarian cancer mouse model, suggesting that cDC1 vaccines represented by CD141+ Clec9a+ cells may be an effective immunotherapy in patients with ovarian cancer." (PMID 36596856, 2023). "In ovarian cancer, BRCA1-mut cancer genes such as AIF1, CD8A, and BST1 showed detrimental prognosis, while in BRCA2-mut ovarian cancer, SEC61A2 and IGFBP3 were associated with shorter survival." (PMID 40647506, 2025). "These include AIF1, CD8A, and BST1 in ovarian cancer BRCA1-mutant cancers, and SEC61A2 and IGFBP3 in BRCA2-mutant ovarian cancer." (PMID 40647506, 2025). "In an animal study with mouse ovarian cancer ID8-Luc peritoneal model, PLD alone, the combination of PLD and IN10018, and the triple combination of PLD, IN10018, and anti-mouse CD8α were evaluated with their anti-tumor effects." (PMID 38373953, 2024).
ovarian carcinoma (continued). "After incorporating the H-/L- expression groups of ICOS, TIGIT, CD8A, and TNFRSF8, the researchers categorized the ovarian cancer samples into 4 groups." (PMID 36157232, 2022). "Genes related to ICB (CTLA-4, PD-L1, and PD-L2) and cytotoxic lymphocytes (CD8A, GZMA, and PRF1) were all highly expressed in type I and II ovarian cancer." (PMID 32793247, 2018). "Genes related with ICB, including CTLA-4, PD-L2, PD-L1, CD8A, GZMA, and PRF1, were all lowly expressed in type III ovarian cancer." (PMID 32793247, 2018). "The higher expression of PD-L1, CD8A, GZMA, and PRF1 in type I and II ovarian cancer indicated that these patients would tend to gain more benefit from anti-PD-1/PD-L1 therapy." (PMID 32793247, 2018).
colon carcinoma (640 papers, 2004 to 2026). "An association between high expression of CD8A and better prognosis has been reported in both lung adenocarcinoma and colon cancer." (PMID 34795691, 2021). "First, only transcriptomic expression of IDO1 and CD8A expression with clinical data was analyzed to predict prognosis in the colon cancer risk subgroups from public databases (TCGA and NCBI-GEO)." (PMID 33425745, 2020). "Then, we conducted CMS classification in the context of the colon cancer risk subgroups because the IDO1/CD8A-stratified risk groups were different from the CMS classification." (PMID 33425745, 2020). "This study investigates the prognosis associations of FAP and CD8a in two colon cancer cohorts and, specifically, explores the possibility that the prognostic capacity of CD8-positive cells differs between cases defined by their FAP status." (PMID 33153037, 2020). "We then performed a clustering analysis of immune-related genes for the colon cancer risk subgroups stratified by CD8A and IDO1 using the TCGA data." (PMID 33425745, 2020). "To further explore associations between IDO1/CD8A stratification and cancer progression or tumor immune status in colon cancer, we utilized a murine model in which mouse colon cancer cells (SL4) were injected into the spleen and developed into liver metastasis." (PMID 33425745, 2020). "As expectedly, high CD8A expression showed significantly better prognosis than low CD8A expression in colon cancer, as CD8 CTL was demonstrated to suppress tumorigenesis immunologically." (PMID 38557819, 2024). "Intriguingly, high B2M expression showed significantly better prognosis than low B2M expression in colon cancer (p = 0.0021) similarly with CD8A, IFNG and TLR4." (PMID 38557819, 2024). "Following a common preclinical combination treatment protocol, the study used a radiolabeled antibody to detect changes in CD8a+ infiltration in murine colon tumors." (PMID 38609844, 2024). "Our previous study has demonstrated that the combined IDO1 and CD8A classifier was more accurate in predicting clinical outcomes than the known methods for molecular subtyping identification in patients with colon cancer." (PMID 35711437, 2022). "Consistent with the TCGA findings, the stratified analysis using IDO1 and CD8A expression revealed a similar trend of worse prognosis for group IV* (CD8AhighIDO1high*) using the independent cohort of colon cancer from NCBI-GEO data set." (PMID 33425745, 2020). "Analyses of a population-based colon cancer cohort demonstrated good prognosis associations of FAP intensity and CD8a density." (PMID 33153037, 2020). "Future research is required to explore the detailed mechanism between the combined IDO1 and CD8A prognostic classifier and tumor development of colon cancer." (PMID 33425745, 2020). "Hierarchical clustering, functional enrichment analyses, and immune infiltration analysis were applied to evaluate the distinctive immune statuses in colon cancer risk subgroups stratified by IDO1 and CD8A expression." (PMID 33425745, 2020). "Although IDO1 expression was associated with the gene signature of CD8 T cells in colon cancer, the different expression patterns of IDO1 and CD8A imply biologically and clinically different behavior." (PMID 33425745, 2020). "In this study, we identified the immunological subtypes of colon cancer based on the expression of IDO1 in combination with CD8A expression, and explored the prognostic values, phenotypes, and functions of distinct subgroups in colon cancer." (PMID 33425745, 2020). "Our aim was to elucidate the prognostic significance of the combination of IDO1 and CD8A expression in colon cancer." (PMID 33425745, 2020). "This study identifies two FAP-defined subgroups of CD8a density-high colon cancers, which differ significantly with regard to outcome and, also, display differences in the composition of the immune environment." (PMID 33153037, 2020).